SIRT1 (sirtuin 1)
Diseases named in the same sentence as SIRT1 in open-access papers (continued):
Sharing a sentence is not in itself a finding about the gene and the disease.
Obesity (continued). "As such, interventions in either mothers or fathers may have favourable impacts on foetal SIRT1 regulation and the associated metabolic pathways, hence reducing the risk of developing obesity and metabolic disorders such as type 2 diabetes and non-alcoholic fatty liver disease." (PMID 33027895, 2020). "For example, miR-204 targets sirtuin 1 (SIRT1) to promote adipogenesis, while miR-93 regulates obesity by inhibiting sirtuin 7 (Sirt7) and T-box 3 (Tbx3)." (PMID 32722316, 2020). "SIRT1, an NAD+-dependent deacetylase, impaired adipogenesis by directly acting as a PPARG co-repressor, thus, counteracting obesity." (PMID 29541908, 2019). "In the present study, we showed that vitamin D-inadequate diet significantly exacerbated obesity-induced intramuscular fat accumulation in rats fed with a HF diet and suppressed AMPK/SIRT1 activities." (PMID 31744213, 2019). "Sirtuin 1(SIRT1) is a NAD+-dependent histone deacetylase which deacetylates proteins that contribute to oxidative stress, aging, obesity, and tumors." (PMID 31097039, 2019). "The influence of vitamin D status on activities of SIRT1 and AMPK involved in obesity-induced muscle fat accumulation through muscle mitochondrial changes has never been evaluated." (PMID 31744213, 2019). "The ability of CAP to enhance SiRT-1 activity to promote the browning phenomenon in WAT and UCP-1-mediated thermogenesis are important for the anti-obesity effect of CAP." (PMID 31197191, 2019). "The striking dichotomy between SIRT1 and SIRT2 in nuclear functions and physiologic effects in lean vs. hyper nutrition with obesity is not fully understood." (PMID 30216989, 2018). "In particular, EA promoted the expression of Sirt1 and deacetylation of histones in WAT, introducing an effective effort to cure obesity and its complications." (PMID 30425749, 2018). "It was found that increased SIRT1 level diminished BDNF signaling which resulted in severe hyperphagia and obesity both in humans and animals." (PMID 30374331, 2018). "The production of 1MNA by nicotinamide N-methyltransferase (NNMT) is proposed to contribute to diet induced obesity through regulation of NAD and ultimately Sirt1 signaling." (PMID 29324762, 2018). "Overall, our data suggest that CACUL1 tightly regulates PPARγ signaling through the mutual opposition between SIRT1 and LSD1, providing insight into its potential use for anti-obesity treatment." (PMID 29233982, 2017). "The interaction of aging and metabolic pathways, including p66SHC, SIRT1, or AMPK/mTOR/S6K, with telomere erosion in the presence of diabetes or obesity is a promising field to reveal how metabolic disorders impact on aging." (PMID 26968134, 2016). "The NAD+-dependent protein deacetylase sirtuin 1 (SIRT1), a key regulator of mammalian metabolism, maintains proper metabolic functions in many tissues, counteracting obesity." (PMID 26655722, 2016). "Firstly, the potent Sirt1 activator, SRT1720, was found to protect the ovarian follicle reservoir in mice against obesity and this was abolished by NAM." (PMID 25938585, 2015). "Further in support of this, NAM also abolished the ability of the highly potent Sirt1 activator, SRT1720, to protect the primordial follicle pool from the detrimental effects of diet-induced obesity in mice." (PMID 25938585, 2015). "Caspase 1 activation can also inactivate sirtuin 1 (SIRT1) by cleavage, where SIRT1 is a NAD+-dependent protein deacetylase with anti-inflammatory properties, and it is recognized to protect against obesity-induced hepatic steatosis and inflammation." (PMID 24379011, 2013). "Very recently, we observed similar effects in our diet-induced obesity model, where APO10LA supplementation (10 mg/kg diet) for 24 weeks significantly induced hepatic SIRT1 protein expression and deacetylation of NF-κB p65 in HFD-fed mice." (PMID 24379011, 2013).
Obesity (continued). "This includes for example the regulation of SIRT1, a protein known to activate PPARG and SREBF1, which contributes to hepatic steatosis in obesity upon ubiquitination and proteasomal stimulation of its degradation." (PMID 24324835, 2013). "Because anti-inflammatory and cell-protective mechanisms mediated by SIRT1 are suppressed in diabetes, small SIRT1 activators are considered to be potential drugs for the treatment of T2DM, obesity, and MetS, among other disorders." (PMID 24278677, 2012). "Consequently, if activation of SIRT1 results in loss of body fat without decreasing caloric intake, this could open the door for novel treatment and prevention strategies for obesity and related diseases." (PMID 22115311, 2011). "We recently reported that these SIRT1 activators, like calorie restriction, improve glucose and insulin homeostasis in three models of T2DM: a C57BL/6 mouse diet-induced-obesity model, an ob/ob mouse model and a Zucker fa/fa model." (PMID 19284563, 2009). "Future studies should focus on further elucidating the downstream effects of dysregulated lipolysis in the context of obesity-related pathologies, as well as exploring potential therapeutic interventions targeting the ZFP36/RNF128/Sirt1 pathway to mitigate metabolic dysfunction." (PMID 41596407, 2026). "Patients without obesity showed higher SIRT1 levels in SAT than in plasma (4.19 ± 1.33 and 1.06 ± 0.12 ng/mL, respectively, p = 0.039)." (PMID 42075052, 2026). "SIRT1, SIRT3, and SIRT6 activation may be a new treatment strategy for various metabolic diseases including diabetes, obesity, and osteoporosis." (PMID 41304967, 2025). "Most studies suggest that SIRT1, SIRT3, and SIRT6 play protective roles in obesity." (PMID 41304967, 2025). "SIRT1 serum levels in LDs did not reflect the amount of body fat and were higher than in normal weight subjects and obesity, and comparable to those measured in AN." (PMID 38732001, 2024). "Moreover, the administration of the SIRT1 activator SRT1720 enhanced the endurance running performance and protected mice against insulin resistance and diet-induced obesity by enhancing oxidative metabolism in their skeletal muscle and other tissues." (PMID 38792610, 2024). "Our study raises the possibility that LBP exerts its effects not only by targeting SIRT1 but also by targeting ATF6, which will further ameliorate the UPR and ER stress and may represent a therapeutic strategy for obesity." (PMID 38606478, 2024). "Resveratrol further increased IRS1, Akt, and TBC1D4 insulin-stimulated phosphorylation and SIRT1 content in myotubes from lean women, but not in women with severe obesity." (PMID 38324260, 2024). "Besides, UDCA has been reported to activate the SIRT1-PGC1α signaling pathway and reduced sterol regulatory element-binding protein-1 (SREBP-1), thus improve lipid metabolism and reduce body weight of obesity mice." (PMID 39425211, 2024). "Collectively, our findings suggest that LBP supplementation alleviates obesity by ameliorating LD accumulation, which might be partially mediated by an ATF6/SIRT1-dependent mechanism." (PMID 38606478, 2024). "Mice lacking Glrx develop MASLD (fatty liver, obesity, dyslipidemia) with a regular diet, while adenoviral Glrx gene transfer activates SirT1 and reverses steatosis." (PMID 39411175, 2024). "The release of the nuclear LC3 pool during starvation is regulated by SIRT1-dependent deacetylation, with LC3 exiting the nucleus in complex with the diabetes- and obesity-regulated nuclear factor (DOR) in preparation for its incorporation into the nascent isolation membrane." (PMID 37014324, 2023). "Our study suggests that the tea mixture nano-formulation is a promising therapeutic agent in the treatment of obesity and may also be beneficial in other metabolic disorders by targeting the AMPK/Sirt-1/Glut-4 pathway." (PMID 37512578, 2023).
Obesity (continued). "SIRT1 is an NAD+-dependent deacetylase, and activation of SIRT1 has multiple biological functions that are beneficial for life extension, including the improvement in metabolic diseases such as NAFLD, diabetes, and obesity." (PMID 37367070, 2023). "Moreover, NNMT knockdown in mice fed HFD protects against diet-induced obesity, with a concomitant increase of WAT NAD+ and modulated expression of several upstream and downstream genes, including SIRT1 targets." (PMID 37761000, 2023). "While age and height did not significantly correlate with SIRT1 gene expression, the obesity characteristics including, weight, weight z-score, BMI, BMI z-score, waist circumference, and waist-to-hip ratio were notably related to SIRT1 expression." (PMID 37862340, 2023). "SIRT1 expression is down-regulated in obesity, revealing significant negative correlations with waist circumference, body mass index (BMI), and insulin resistance (IR)." (PMID 37511397, 2023). "Protective effects of the drugs may be through correlations between SIRT-1/adipokines/IGF-1 and PPARγ, improving the cross-talk between insulin resistance, obesity markers, liver dysfunction, and TNF-α." (PMID 36991247, 2023). "In the following sections, we describe the mechanisms by which SIRT1 and the modulation of NAD+ metabolism are involved in the pathophysiology of kidney diseases, with special emphasis on SIRT1 alterations in AKI, chronic renal failure, obesity, and DKD." (PMID 35277012, 2022). "Sirtuins appear to have a complex but generally protective effect against obesity; increasing NAD+ levels or SIRT1 and SIRT6 activity may be a helpful therapeutic strategy for preventing and treating type 2 diabetes, MetS, and insulin resistance." (PMID 36361416, 2022). "In addition, AMP-activated protein kinase/sirtuin 1 (AMPK/SIRT1), fibroblast growth factor-19/21 (FGF19/21), Janus kinase/signal transducer and activator of transcription (JAK/STAT), and Notch signaling pathways implicated in obesity could also be investigated." (PMID 35215280, 2022). "We observed that seabuckthorn powder reversed HFD-induced obesity, improved systemic insulin sensitivity, and promoted thermogenic program in BAT and WAT, which might be attributed to the activation of the AMPK/SIRT1 pathway." (PMID 35889860, 2022). "BMI was the strongest predictor of BMD in our cohort, despite the lower levels of SIRT1 and the higher levels of sclerostin seen in the group of patients with obesity should have predicted a negative effect on bone." (PMID 35267956, 2022). "In this study, LT supplementation increased muscle expression of transcripts related to fatty acid oxidation (CPT1, PGC-1a, Tfam, Nrf1, SIRT1, and UCP2) without obesity-induced muscle loss." (PMID 35678694, 2022). "It must be said that obesity decreases autophagy via the mechanistic target of rapamycin complex 1 (mTORC1) activation and reduces the function of AMP-activated kinase (AMPK) and sirtuin-1 (SIRT1)." (PMID 36362220, 2022). "Thus, this study indicates that stimulation of the SIRT1-PGC-1α signaling in skeletal muscle has a significant role in mediating the beneficial effects of BS21 on lipid and glucose metabolism of obesity." (PMID 35276805, 2022). "Similarly, high-dose supplementation of resveratrol, a natural inducer of SIRT1, improves the BMD of male patients with obesity." (PMID 35267956, 2022). "Also, it has been suggested that alpha-mangostin exhibits its anti-obesity effects by activating hepatic expression of AMPK, sirtuin 1 (SirT1), and peroxisome proliferator-activated receptor γ (PPARγ)." (PMID 35655598, 2022). "In another study, SIRT1 mRNA expression in peripheral blood mononuclear cells (PBMC) was also increased in healthy volunteers without obesity after 8 weeks of the 16:8 early TRF." (PMID 36432465, 2022).
Obesity (continued). "Also, SirT1, AMPK, and PPAR pathways are thought to be involved in alpha-mangostin regulating hepatic steatosis and obesity in high-fat diet mice." (PMID 35655598, 2022). "Lipid and glucose metabolism from muscle can be regulated by stimulation of the AMPK-SIRT1-PGC-1α signaling pathway, and the activities of AMPK, SIRT1, and PGC-1α can be inhibited by obesity and other metabolic diseases, which impair lipid and glucose metabolism in skeletal muscle." (PMID 35276805, 2022). "Yet, under duress of overnutrition, obesity and insulin resistance, hepatocyte NAMPT selectively activates SIRT1-dependent transcriptional regulation to attenuate diet-induced hepatic and extrahepatic metabolic derangements in energy homeostasis and glucose homeostasis." (PMID 35228549, 2022). "To verify whether the anti-obesity and intestinal barrier protection effects of SNP on HFD-fed mice were also mediated by AMPKα/SIRT1 signaling, we tested the colonic expression of these signals." (PMID 34600475, 2021). "Thus, obesity increases the probability of lung diseases, including COPD and pulmonary fibrosis, in part by suppressing sirt-1 production." (PMID 35115954, 2021). "Furthermore, the results illustrate that the mRNA expression levels of PCM1, SIRT1, EEF1G, PTEN and RPS2 were significantly decreased in the obesity compared with the control group." (PMID 34248836, 2021). "Some studies have shown that the ethyl acetate fraction of chrysanthemum indicum (CIEA) might be beneficial for preventing obesity, and in vitro chrysanthemum morifolium flower extract inhibits adipogenesis of 3T3-L1 cells via AMPK/SIRT1 pathway activation." (PMID 34439559, 2021). "In their study, they showed that SIRT1 promotes a beneficial metabolic effect through interaction with PPARγ, leading to insulin sensitization, and implied a therapeutic potential of TZD and SIRT1 agonist combination therapy for obesity." (PMID 33467433, 2021). "Due to the crosstalk between gut dysfunction, obesity, AMPK/SIRT1 signaling, and the role of SNP on AMPKα phosphorylation, we hypothesized that SNP protected against HFD induced gut dysfunction via activating AMPKα/SIRT1 signaling." (PMID 34600475, 2021). "Our experiments on LPS stimulated Caco-2 cell monolayers that mimicked intestine epithelium barrier dysfunction and HFD-fed mice that were complicated by gut dysfunction found that SNP alleviated obesity and gut dysfunction by recovering HFD inhibited AMPKα/SIRT1 signaling." (PMID 34600475, 2021). "Mice lacking SIRT1 in proopiomelanocortin (POMC) neurons on a high-fat diet (HFD) are vulnerable to diet-induced obesity because of reduced energy expenditure even when regular chow diet (RCD)-fed conditions do not alter body weight or adiposity in these mice." (PMID 34046646, 2021). "In HFD, caspase-1 cleaves an inactivated SIRT1 protein in adipose tissues, and the adipocytes in the absence of the SIRT1 gene show spontaneous obesity." (PMID 32545788, 2020). "Sirt1-deficient mice lacked AMPK activity and had increased SREBP-1c expression that triggered hepatic steatosis and obesity." (PMID 32210812, 2020). "A previous study demonstrated that TGR5 activation inhibited oxidative stress and induced mitochondrial biogenesis by promoting SIRT1, SIRT3, and Nrf-1 expression, indicating a protective role for TGR5 inhibiting obesity-related and diabetes-related kidney disease." (PMID 33298860, 2020). "Diet-induced obesity impaired hippocampal performance in spatial memory, synaptic plasticity tested through LTP and decreased the levels of memory related genes (Ppp1cb, Reln, Sirt1) in the hippocampus." (PMID 32635190, 2020). "The mRNA expression of SIRT1 was decreased in WAT of diabetic SD rats and IR-3T3-L1 adipocytes, it is consistent that reduced expression of SIRT1 in human obesity may foster visceral adipose tissue expansion." (PMID 32595495, 2020).
Obesity (continued). "It has been reported that the raise of SIRT-1-mediated PPARγ deacetylation further facilitated the interaction of PPARγ and PRDM16, which eventually promoted brown features in white adipocytes to prevent obesity." (PMID 33551999, 2020). "SIRT1 activation exhibited various beneficial biofunctions, including extending lifespan, delaying senescence, and improving metabolic diseases, such as NAFLD, diabetes, and obesity." (PMID 33328983, 2020). "In this work, we aim to figure out whether EA can activate SIRT-1-dependent PPARγ deacetylation pathway and PGC-1α-TFAM-UCP1 pathway to promote the browning of WAT and mitochondria biogenesis, so as to combat obesity." (PMID 33551999, 2020). "Mice lacking the SIRT1 gene develop obesity and IR and have ectopic lipid accumulation, as well as increased AT inflammation when fed a HFD." (PMID 32358737, 2020). "SIRT1, with a decrease in ERS, and activation of silencing regulator 1, has been found in the testicular tissues of obese mice, which reveal that ERS stimulation is involved in the process of obesity-related male subfertility." (PMID 32528287, 2020). "In the present study, we found that BBR upregulated SIRT1 expression in adipose tissue, leading to induced activation of the AMPK pathway and suppression of obesity-related inflammatory response, resulting in improvement of local and systemic insulin resistance." (PMID 33390968, 2020). "SIRT1 had a high predictive power mostly in the group of patients with obesity, where we observed no substantial differences in the predictive power of the three plasma variables." (PMID 33202604, 2020). "In addition, SF1 specific SIRT1 deletion induced insulin resistance while SIRT1 overexpression in SF1 resulted in insulin sensitivity and prevention of diet-induced obesity in skeletal muscles of transgenic type 2 diabetic mice." (PMID 33330467, 2020). "The specific aim of this study is to evaluate effects of tartary buckwheat extract (TB) on obesity-induced adipose tissue inflammation and muscle peroxisome proliferator-activated receptor-γ coactivator (PGC)-1α/sirtulin 1 (SIRT1) pathway in rats fed a high-fat diet." (PMID 30889894, 2019). "Interestingly, Sirt1 expression was also shown to be affected by aging in the ARC, and it has been suggested that conditional knock-in of Sirt1 in AgRP and POMC neurons could protect against aging-associated obesity by inhibiting feeding and stimulating energy expenditure." (PMID 31309172, 2019). "Resveratrol, which activates SIRT1, inhibits HFD-induced obesity." (PMID 31618980, 2019). "Indeed, PG extract increased thermogenic gene expression (such as SIRT1, PPARα, UCP1, PGC1α), thereby inducing the browning of white adipose tissue, resulting in an anti-obesity effect." (PMID 31615016, 2019). "SRT1720, a SIRT1 activator, ameliorates fatty liver through suppressing the expression of lipogenic enzymes, including SREBP-1c, acetyl-CoA carboxylase, and fatty acid synthase, in obesity and insulin resistant mice." (PMID 30574122, 2018). "Resveratrol, a SIRT1 activator, had a protective effect against diet-induced insulin resistance in mice and decreased plasma glucose and triglycerides, homeostatic model assessment (HOMA) index and inflammation markers in humans with obesity." (PMID 29417372, 2018). "Similarly, pharmacological stimulation of SIRT1 by sirtuin-activating compounds (STACs), such as resveratrol, SRT1720, and SRT2104, has been reported to protect against HFD-induced obesity and insulin resistance in animals and humans." (PMID 30513672, 2018).